SMARCA2 (SWI/SNF related BAF chromatin remodeling complex subunit ATPase 2)
Diseases named in the same sentence as SMARCA2 in open-access papers (continued):
Sharing a sentence is not in itself a finding about the gene and the disease.
adenocarcinoma (9 papers, 2013 to 2025). A common cancer characterized by the presence of malignant glandular cells. "Loss of SMARCA2 and SMARCA4 was frequent in solid-predominant adenocarcinomas and tumors with low levels of bronchial epithelial markers, i.e., TTF-1, CK7, and E-cadherin." (PMID 39888726, 2025). "Positive nuclear staining of SMARCA2 and concomitant nuclear staining of SMARCA2 and SMARCA4 were both associated with better five-year survival in 300 NSCLC cases (150 adenocarcinoma and 150 SCC)." (PMID 39888726, 2025). "In the adenocarcinoma components, SMARCA2 was intact (B, × 200) and PD-L1 was negative (C, × 200); conversely, in the undifferentiated components, SMARCA2 showed lost (H, × 200) and PD-L1 showed positive (I, × 200)." (PMID 36464671, 2022). "H&E image of case 17 (A, × 40) showed the coexistence of normal glands, well-differentiated adenocarcinoma components, and undifferentiated components in which SMARCA2 expression was reduced (B, × 200), and ARID1A expression was intact (C, × 200)." (PMID 36464671, 2022). "His adenocarcinoma was HepPar1-positive and showed loss of SMARCA2 and PBRM1 (data not shown)." (PMID 33506327, 2021). "This study aimed to investigate the clinical relevance of immunohistochemical expression of proteins of the SWI/SNF complex, SMARCA2, SMARCA4 SMARCB1, ARID1A, ARID1B, and PBRM1 in 477 adenocarcinomas of the stomach and gastroesophageal junction." (PMID 34359794, 2021). "Although the loss of SMARCA2 was not significantly more frequent in HNF4α-positive adenocarcinomas, two of the four HNF4α-positive Grade 3 adenocarcinomas that expressed SMARCA4 showed the loss of SMARCA2." (PMID 38710944, 2025). "Depletion of SMARCA4, but not of SMARCA2, significantly reduced proliferation of the adenocarcinoma cell line LNCaP and the LNCaP-derived androgen-independent CRPC-Adeno cell line C4-2, in line with previous findings." (PMID 33144576, 2020). "SMARCA2 and/or its binding protein SMARCA4 is absent or disrupted in approximately 17% of all human adenocarcinomas." (PMID 23668334, 2013).
neurodevelopmental disorder (4 papers, 2019 to 2025). A behavioral and cognitive disorder with onset during the developmental period that involves impaired or aberrant development of intellectual, motor, or social functions. "Interestingly, mutations in SMARCA2 have been associated with neurodevelopmental disorders." (PMID 36261270, 2022). "Nicolaides‐Baraitser syndrome (NBS) is an ultrarare SMARCA2‐related neurodevelopmental disorder, whose cutaneous hallmarks traditionally include early hypotrichosis and coarse, sparse scalp hair." (PMID 40881542, 2025).
infection (3 papers, 2018 to 2025). The state of being infected such as from the introduction of a foreign agent such as serum, vaccine, antigenic substance or organism. "Infection with L. monocytogenes causes H3K18 deacetylation of many genomic proteins in colon cells, including SMAD1, IRF2, SMARCA2, and CXCL12." (PMID 35572672, 2022). "Analysis of SMARCA2-silenced A549-wt cells pretreated with 1000 U/mL IFN-α 24 h prior to H7N7-RL infection revealed that in fact 8.6% of cells were positive for both MxA and viral nucleoprotein (NP), compared to 0.1% in the non-targeting (NT) control knockdown." (PMID 29391557, 2018).
hematologic malignancies (2 papers, 2023 to 2024). "Regarding SMARCA2, its individual role in hematological malignancies remains unknown." (PMID 36810086, 2023). "In hematological malignancies, most of the SWI/SNF subunit-targeting therapies described so far are based on small inhibitors targeting either SMARCA4/SMARCA2 or BRD9." (PMID 36810086, 2023). "Additionally, a novel SMARCA4/SMARCA2 inhibitor, FHD-286, is being evaluated in a phase 1 dose escalation study in patients with advanced hematologic malignancies (ClinicalTrials.gov ID NCT04891757)." (PMID 39439958, 2024).
hematological cancers (2 papers, 2022 to 2023). "Various SWI/SNF genes, such as ARID1A/1B/2 and SMARCA2/4, are recurrently mutated across a wide variety of hematological and non-hematological cancers, whereas others, such as BCL7A, are specifically mutated in certain hematological malignancies." (PMID 36810086, 2023). "Indeed, it has been shown that several hematopoietic cancer cell lines are exquisitely sensitive to dual SMARCA4/SMARCA2 catalytic inhibitors." (PMID 36810086, 2023).
cardiovascular disease (1 paper, 2024). "Therefore, SMARCA4 and SMARCA2 are not ideal targets for cardiovascular disease treatment." (PMID 38247859, 2024).
SMARCA2 also shares sentences with these, for which no sentence is quoted: hepatocellular carcinoma (7 papers); glioblastoma (4); Kabuki syndrome (3); adenoma (2); age-related macular degeneration (2); brain tumor (2); CHARGE syndrome (2); genetic diseases (2); intellectual disability syndrome (2); lung disease (2); metastatic tumors (2); pancreas carcinoma (2); urothelial carcinoma (2); Weaver syndrome (2); adrenocortical carcinoma (1); Alzheimer disease (1); astroblastoma (1); atopic dermatitis (1); attention deficit-hyperactivity disorder (1); autism spectrum disorder (1); autosomal dominant disease (1); autosomal dominant mental retardation (1); bipolar disorder (1); chronic lymphocytic leukemia (1); Cirrhosis (1); Cohen-Gibson syndrome (1); congenital glaucoma (1); coronavirus disease 2019 (1); diabetes (1); diffuse midline glioma (1).
A further 43 diseases each share a sentence with SMARCA2 in 1 paper.